TNF (tumor necrosis factor)
Diseases named in the same sentence as TNF in open-access papers (continued):
Sharing a sentence is not in itself a finding about the gene and the disease.
Insulin resistance (continued). "The sphingolipid ceramide is the main culprit that combines a plethora of nutrients (e.g., saturated fatty acids) and inflammatory cytokines (e.g., TNFα) to the progression of insulin resistance." (PMID 31496996, 2019). "Compared with placebo vitamin D supplementation:↓ IL-6 and ↑ hs-CRPNo changes in TNF-α and insulin resistance." (PMID 31068933, 2019). "Serum levels of IL-6 and TNF-α and insulin resistance were significantly higher in cases than the controls." (PMID 30635365, 2019). "MiR-138-5p contributed to the TNF-α-induced insulin resistance through inducing autophagy in HepG2 cells by regulating SIRT1." (PMID 30736838, 2019). "Genes encoding secreted factors such as TNFα and SAA3, that are generally associated with adipose tissue inflammation and insulin resistance, were also upregulated in the gonadal fat of HFD-fed Siah2KO female mice, despite their insulin sensitivity." (PMID 30987673, 2019). "In support of this argument, TNF-α, IL-6, IL-8, CCL2, CCL4, CCL5, and CCL19 were found to be implicated with metabolic inflammation or insulin resistance in various tissues and organs." (PMID 31718015, 2019). "Erchen decoction and Linguizhugan decoction reduce the level of TNF-α in diet-induced insulin-resistant rats to improve IR, similar to the pharmacological action of thiazolidinedione." (PMID 31258478, 2019). "Oxidative stress is associated with instigating insulin resistance by up-regulating the production of pro-inflammatory cytokines, such as CRP and TNF-α, which induce damage to proteins in the insulin cascade." (PMID 30723416, 2019). "We observed that FGF-1 treatment significantly improved insulin resistance in TNF-α-induced insulin resistance in vitro and in vivo." (PMID 31866871, 2019). "In 1993, Hotamisligil found that TNF-α played an important role in regulation of insulin resistance in obese rats." (PMID 31548850, 2019). "The current study is aimed at investigating the effect of TNF-α elimination on the palmitate-induced insulin resistance." (PMID 30863203, 2019). "Two candidate gene systematic reviews focused on SNPs in the TNF-α gene, which is a pro-inflammatory cytokine that has been associated with PCOS, ovarian function, and ovulation, and is a known mediator of insulin resistance." (PMID 31623391, 2019). "Carnitine has been reported as highly efficient in the downregulation of pro-inflammatory cytokines TNF-α and IL-6 in murine models of cancer cachexia, liver fibrosis and in blocking TNF-α-induced insulin resistance in skeletal muscle cells." (PMID 31718684, 2019). "In the current study, we showed that both EWH and IRW can improve insulin resistance in TNF-α-treated L6 skeletal muscle cells." (PMID 29955954, 2019). "In summary, the present study confirms the protective effects of FGF-1 in DIO- or TNF-α-induced insulin resistance mice." (PMID 31866871, 2019). "In mice models, probiotics had positive effects on oxidative and inflammatory liver damage mediated by c-Jun N-terminal kinase (JNK) and NF-KB correlated with TNF-α regulation and insulin resistance." (PMID 30658519, 2019). "The same study also demonstrated that FRB extracts inhibited the expression of tumour necrosis factor-alpha (TNF-α), resulting in an increased insulin sensitivity, reduced insulin resistance and hyperglycaemia." (PMID 31878222, 2019). "In 3T3-L1 mouse adipocytes, increased expression of GM3 upon TNFα stimulation induces insulin resistance through interaction between GM3 and the insulin receptor." (PMID 31861196, 2019). "In fat pad of obese rodents and humans, overexpression of TNFα promotes insulin resistance through increased serine phosphorylation of the IRS-1 receptor and decreased insulin receptor kinase activity." (PMID 31496996, 2019).
Insulin resistance (continued). "One century later, the discovery that the pro-inflammatory cytokine, Tumor Necrosis Factor-alpha (TNF-α), is secreted by macrophages within adipose tissue and causes insulin resistance established a direct link between immunity and metabolism." (PMID 31505811, 2019). "M1 macrophages secrete the proinflammatory cytokines TNF-α, IL-1β, and IL-6, which promote insulin resistance and the accompanying deleterious metabolic effects, as well as synthesis of C-reactive protein." (PMID 31015797, 2019). "Inflammatory cytokines such as TNF-α and IL-6 promote the development of insulin resistance, and a recent study has reported that anti-inflammation agents showed efficacy in reducing blood glucose level." (PMID 30453687, 2018). "Elevated TNF-α levels induce insulin resistance by down-regulating the tyrosine kinase activity of the insulin receptor and decreasing the expression of GLUT-4 glucose transporters." (PMID 29189992, 2018). "TNF-α and IL-6 not only drive keratinocyte proliferation and differentiation but also increase insulin resistance and promote proinflammatory cytokines release." (PMID 29546055, 2018). "Inflammatory cytokines, including TNF-α and IL-6, are thought to contribute to the development of insulin resistance through the activation of several stress kinases, such as JNK." (PMID 29433422, 2018). "Pro-inflammatory cytokines such as tumor necrosis factor α (TNFα), interleukin-6 (IL-6), and resistin can promote insulin resistance that can, in turn, be ameliorated by a decrease in visceral adipose tissue." (PMID 29141990, 2018). "Inflammatory adipokine TNF-α is one of the factors responsible for this insulin resistance through activation of TNF receptor-JNK signaling pathway, resulting in the phosphorylation of serine residue of IRS-1." (PMID 29872751, 2018). "These associated genes were enriched in three KEGG pathways related to insulin resistance, adipocytokine signaling and TNF signaling." (PMID 30619480, 2018). "Animal and human models have demonstrated innate immunity as well as experimental in vivo induction of inflammation via bolus of an inflammatory cytokine such as TNF-α or IL-6, results in release of adipokines and generation of peripheral insulin resistance." (PMID 29910818, 2018). "Differences in insulin, homeostasis model assessment of insulin resistance, triglyceride, free fatty acid, tumor necrosis factor-α and monocyte chemotactic protein-1 levels were statistically significant across the three groups (all P < 0.05)." (PMID 30355361, 2018). "TNFα (acting through NFκB, a heterodimer of p65 and p50) also induces insulin resistance by elevating ROS in 3T3-L1 adipocytes." (PMID 30310815, 2018). "In humans, circulating TNFα levels are increased during aging, suggesting a correlation between vascular insulin resistance and plasma TNFα levels." (PMID 29464018, 2018). "Several inflammatory cytokines, such as tumor necrosis factor-α (TNF-α) and interleukin-6 (IL-6), have been implicated in the causation of insulin resistance and appear to confer an increased risk of microvascular complications in type 2 diabetes mellitus." (PMID 30526660, 2018). "Other factors including PTP1B and especially TNF-α, slowly return toward normal values, which would contribute to maintain leptin and insulin resistance at the early stages." (PMID 29367725, 2018). "Accordingly, a marked increase of TNF-alpha, the main pro-inflammatory cytokine involved in insulin resistance development, was detected in the gastrocnemious of HFHS animals (p<0.05 vs Control)." (PMID 29342166, 2018). "Pre-treatment with TNFα induced insulin resistance, indicated by reduced AKT S473 phosphorylation in response to insulin." (PMID 29661693, 2018). "Eventually, increased serum levels of PAI-1, ET- 1, tumor necrosis factor-α (TNF-α), interleukin-6 (IL-6), and C-reactive protein (CRP), reflect association of insulin resistance with low-grade inflammation and endothelial dysfunction." (PMID 30170601, 2018).
Insulin resistance (continued). "Proinflammatory cytokines such as tumor necrosis factor α(TNFα) and genetic defects (i.e., Akt) induce insulin resistance." (PMID 30602666, 2018). "Taken together, these data suggest that SRA promotes adipocyte differentiation and insulin sensitivity through up-regulating insulin signaling and simultaneously inhibiting signaling downstream of TNFα, which otherwise would promote insulin resistance." (PMID 30238005, 2018). "Third, reduction in the duration of sleep leads to elevation of the levels of cortisol, IL-6, and TNFα, resulting in activation of the sympathetic nervous system that promotes insulin resistance." (PMID 29364963, 2018). "Since TNF-α, a mediator of inflammation, plays a major role in the pathogenesis of NAFLD and development of insulin resistance and impaired glucose tolerance, we determined the effect of ZA-M on OA-induced production of TNF-α." (PMID 29507591, 2018). "Inflammatory processes, especially those involving the pro-inflammatory cytokine TNFα and its signalling pathway, play a key role in insulin resistance and glucose intolerance." (PMID 30390669, 2018). "It has also been proposed that TNF-α increasing in GDM can suppress transcription of adiponectin that results in insulin resistance and hyperinsulinemia." (PMID 29387323, 2018). "The stimulation of NF-κB increased the levels of downstream inflammatory factors such as TNF-α, IL-1β, and IL-6, which promoted the insulin resistance in the liver." (PMID 30453687, 2018). "Together, our results indicated that 5-PAHSA can significantly reduce high insulin- and TNF-α-induced insulin resistance in HepG2 cells and 3T3-L1 cells." (PMID 30666198, 2018). "Like CRP, TNF-α is considered a link between hypertriglyceridemia, inflammation, and insulin resistance." (PMID 29189992, 2018). "Increases in circulating TNF-α has also been suggested to be related to insulin resistance and augmented systemic inflammation." (PMID 30114249, 2018). "Mice transgenic for the HCV core gene exhibit overexpression of tumor necrosis factor-alpha (TNF-α), and TNF-α-dependent insulin resistance." (PMID 29411291, 2018). "The relative ratios of adiponectin/TNF-α, adiponectin/IL-1β, adiponectin/IL-10, TNF-α/IL-10 and IL-1β/IL-10 have been shown to be strongly correlated with the insulin resistance/sensitivity indexes (HOMA-IR and QUICKI)." (PMID 29785210, 2018). "Superoxide anions in turn trigger production of inflammatory cytokines, such as interleukin (IL)-1β, IL-6, or tumor necrosis factor (TNF)-α, which augment both inflammatory responses and insulin resistance." (PMID 29457119, 2018). "Inflammation can induce the release of the cytokine tumor necrosis factor-alpha (TNF-α), which produces insulin resistance by the inhibition of the insulin receptor tyrosine kinase activity." (PMID 30154946, 2018). "Germane to disordered metabolism in DMD, CHI3L1 also counteracts TNFα-induced insulin resistance in muscle cells." (PMID 29554127, 2018). "Adipocytokines are adipocyte hormones that are involved in the regulation of metabolism and insulin resistance such as TNF-α, adipokines, and leptin." (PMID 30563117, 2018). "High tumor necrosis factor (TNF)-α and low adiponectin levels are associated with NAFLD, independently of insulin resistance." (PMID 31595238, 2018). "TNF-alpha combined with hypoxia was most able to mimic in vivo DIO-induced adipose insulin resistance." (PMID 30697159, 2018). "Patients and cows with NASH displayed high blood NEFAs, TNF‐α and IL‐6 concentrations, mitochondrial dysfunction and insulin resistance." (PMID 29602237, 2018). "For example, various agents including TNF-α, Interleukin-1 (IL-1), IL-6, free fatty acids, dexamethasone, and high insulin were used to make models of insulin resistance in 3T3-L1 adipocytes." (PMID 30445954, 2018).
Insulin resistance (continued). "They identified that the neutralization of TNF by anti-TNF-α antibodies mitigated the resistance of these animals to insulin action, establishing a link between inflammation, insulin resistance, and hyperglycemia." (PMID 29601492, 2018). "Consistent with previous studies, some clinical trials suggest that increased TNF level results in impaired glucose homeostasis and insulin resistance in patients with T2DM." (PMID 29497383, 2018). "Liver insulin resistance leads to increased production of glucose, lipoproteins, inflammatory factors such as TNF-α and interleukin 6 (IL-6), and coagulation factors such as fibrinogen A (FGA), fibrinogen B (FGB) and plasminogen activator inhibitor-1 (PAI)." (PMID 29709004, 2018). "The results indicated that rising Lee's index, hyperlipidemia, insulin resistance, and increasing inflammation factors including NF-κB, TNF-α, and Macrophages 1 were determined in DIO rats while EA is exhibiting an effective intervention." (PMID 30425749, 2018). "We chose the pro-inflammatory cytokine TNFα, a well-characterized inducer of cellular insulin resistance." (PMID 29661693, 2018). "TNF-α is a cell signalling protein that is responsible for metabolic imbalances such as insulin resistance and altered lipid and carbohydrate metabolism." (PMID 30114249, 2018). "In this model, adipocytes secrete proinflammatory cytokines like TNF which is able to inhibit insulin signaling, leading to insulin resistance." (PMID 29482543, 2018). "In the same sense, TNF-α infusion in healthy individuals is able to induce muscle insulin resistance by increasing phosphorylation of p70 S6 kinase, extracellular signal-regulated kinase −1/2 (ERK-1/2), and c-Jun NH2 terminal kinase (JNK)." (PMID 29675435, 2018). "Such demonstrated roles in barrier maintenance in the context of the gut-liver axis have been the basis for anti-TNF therapy such as infliximab, which is effective in reversing liver steatosis and correcting insulin resistance in animal models." (PMID 30345259, 2018). "Especially, TNF is known to trigger insulin resistance and was also highly elevated at an insulin resistant stage in liver and fat in the old HFD mice." (PMID 29426925, 2018). "After over 70% of 3T3-L1 cells differentiated, cells were treated with TNF-α and incubated in hypoxic conditions for 24 h to induce insulin resistance." (PMID 30445954, 2018). "Although TNF-α elicits insulin resistance in the hepatocytes, adipocytes, and activates skeletal muscle cells and phosphorylation of IRS-1 on serine residue is a common event, detailed signaling pathway is different in these cells." (PMID 29872751, 2018). "LP increases serum TNF-α and IL-6 concentrations and induces insulin resistance while ADN has anti-inflammatory properties and decreases the release of proinflammatory mediators." (PMID 30246011, 2018). "It has been reported that TNF-α induced insulin resistance in skeletal muscles is attributed to the induction of IRS-1 phosphorylation on serine residue followed by the deterioration of insulin signaling." (PMID 29872751, 2018). "Surprisingly, MC-T were resistant to TNF-alpha induced insulin resistance, while MC-S developed insulin resistance under similar condition." (PMID 29968746, 2018). "Increased level of inflammatory cytokines, such as IFN-γ, IL-1β, IL17A, IL6, and TNF-α, is also related to insulin resistance, and increased anti-inflammatory cytokines can improve glucose metabolism which regulates insulin sensitivity." (PMID 29541033, 2018). "A number of epidemiological and animal studies have examined the relationship between hepatic insulin resistance and increased production of inflammatory factors such as TNF-α and IL-6." (PMID 29709004, 2018). "It has also been known that many extracellular agents (free fatty acids, H2O2, TNF-α) contribute to insulin resistance." (PMID 30544942, 2018).
Insulin resistance (continued). "Specifically, 5-PAHSA treatment significantly increased insulin stimulated glucose uptake, thus improved insulin resistance induced by high insulin/TNF-α." (PMID 30666198, 2018). "We show that Type I and type II primary myotubes present specific mRNA and myokine signatures as well as a different sensitivity to TNF-alpha induced insulin resistance." (PMID 29968746, 2018). "In the present work, we have established human in vitro models of skeletal muscle cells isolated from type I and type II muscles and study their sensitivity to TNF-alpha induced insulin resistance." (PMID 29968746, 2018). "TNF-α not only promotes inflammation, but also induces insulin resistance by inhibiting insulin receptor activation." (PMID 30246011, 2018). "As BLEx treatment restored the 2-NBDG uptake under TNF-α treatment, BLEx is a promising material that is capable of promoting insulin signaling and alleviating insulin resistance." (PMID 29872751, 2018). "TNF-alpha and dexamethasone are inducers of insulin resistance, respectively inhibiting insulin receptor tyrosine kinase activity or inducing whole body insulin resistance without affecting GLUT4 translocation machinery." (PMID 30697159, 2018). "Extensive cell culture experiments using a dexamethasone as well as a TNF-induced model of insulin resistance were able to show that both agents induced VDR expression." (PMID 30558244, 2018). "TNF-alpha interferes with insulin signaling to produce insulin resistance in the insulin signaling pathway and promotes apoptosis through NF-KB in the apoptosis pathway." (PMID 33385166, 2018). "A significant reduction in mRNA expression levels of monocyte chemoattractant protein-1 and tumor necrosis factor-α (TNF-α) was observed, which is believed to be involved in insulin resistance induction." (PMID 30558294, 2018). "The inhibition of NF-κB activation in drug-treated animals provides an explanation for the reduced serum levels of TNF-α and IL-6 and the improvement in the sepsis-induced insulin resistance process." (PMID 29760586, 2018). "Several studies have shown that TNFa and IL-6 are involved in the development of insulin resistance and blocking of TNF-alpha activity with TNFa antagonists results in improved insulin sensitivity." (PMID 29954107, 2018). "Studies involving mice have shown positive correlation between the quantity of TNF-α and insulin resistance." (PMID 30914847, 2018). "As an inhibitor of TNF-α expression, IL-10 is recognized as an efficient anti-inflammatory cytokine, which can ameliorate insulin resistance and hyperglycemia." (PMID 30186548, 2018). "In the obese state, the adipocytes increase secretion of pro-inflammatory chemokines and cytokines, such as MCP-1, TNFα or interleukins (ILs) which are involved in insulin resistance." (PMID 29507613, 2018). "IL10 has been shown to be able to ameliorate inflammation in obese adipose tissue and insulin resistance induced by proinflammatory cytokines, TNF-α and MCP-152,53." (PMID 29545532, 2018). "The similar positive correlations between extracellular HSP70 and TNF were observed by Krause and colleagues in plasma samples of the elderly (mean age 63.4 ± 4.4 years) in their studies on insulin resistance." (PMID 30534181, 2018). "A low C-HDL, and high levels of NEFA, triglycerides, IL-6, TNF-α and CRP have been previously implicated in the development of insulin resistance." (PMID 30400254, 2018). "As phosphorylation at tyrosine residues is essential for the initiation of intracellular signaling cascade and normal insulin action, TNFα leads to insulin resistance." (PMID 29576769, 2018). "In this sense, prior studies suggest a positive relationship between markers of chronic inflammation, including CRP, IL-1β, IL-6, and TNF-α, and insulin resistance." (PMID 29561774, 2018).